SDC1 (syndecan 1)
Diseases named in the same sentence as SDC1 in open-access papers (continued):
Sharing a sentence is not in itself a finding about the gene and the disease.
capillary leak syndrome (1 paper, 2026). A syndrome characterized by leakage of intravascular fluids into the extravascular space. "Transfusions were associated with modest increases in extracellular water and elevated serum levels of angiopoietin-2 and syndecan-1, consistent with Capillary Leak Syndrome, although absolute ECW differences were small." (PMID 41938900, 2026).
cardiomyopathy (1 paper, 2019). A disease of the heart muscle or myocardium proper. "Various studies have previously confirmed an association not only between HCV infection and cardiomyopathy but also between HCV infection and the expression of syndecan-1." (PMID 31815014, 2019).
cerebral edema (1 paper, 2025). "Individuals exhibiting CT features consistent with cerebral edema demonstrated higher levels of SDC-1, CD44s, sTM, and microalbuminuria; however, statistical significance was reached only for microalbuminuria in patients with cistern compression." (PMID 41586103, 2025).
cervical intraepithelial neoplasia (1 paper, 2022). "On the other hand, the ECM receptor Syndecan-1 (Sdc-1) is differentially expressed in cervical intraepithelial neoplasias and carcinoma in situ." (PMID 35155241, 2022).
chronic asthma (1 paper, 2021). An asthma that is characterized by the development of persistent airway inflammation and recurrent attacks of breathlessness and wheezing, which vary in severity and frequency. "Changes in SDC-1 expression in the airways of mice with acute and chronic asthma were detected by immunofluorescence." (PMID 34671356, 2021). "The present study was the first to demonstrate the involvement of SDC-1 in airway remodeling in chronic asthma in vivo and in vitro." (PMID 34671356, 2021). "The protein level of SDC-1 in the human subjects with chronic asthma was detected by immunohistochemistry." (PMID 34671356, 2021). "The present study also found an interesting phenomenon that SDC-1 expression in bronchial epithelial and periductal cells decreased in humans and mice with acute asthma stage, whereas that in humans and mice with chronic asthma stage substantially increased." (PMID 34671356, 2021). "The similarities in SDC-1 overexpression in mice and humans with chronic asthma suggested that airway remodeling had a conserved effect across species." (PMID 34671356, 2021). "The mice with OVA-induced chronic asthma showed higher levels of inflammation and collagen deposition as well as SDC-1, p-Smad3, collagen I and α-SMA expression than the control group." (PMID 34671356, 2021). "The present study was the first to uncover SDC-1 overexpression in the airways of humans and mice with chronic asthma." (PMID 34671356, 2021). "In addition, Masson staining indicated that substantial amounts of collagen were deposited around the bronchial duct in the subjects with chronic asthma, suggesting the possible involvement of SDC-1 in airway remodeling." (PMID 34671356, 2021). "Overall, the present study was the first to demonstrate that the high expression of SDC-1 in the trachea of patients with chronic asthma is closely related to airway remodeling, and SDC-1 may regulate collagen deposition in epithelial cells or fibroblasts through the TGFβ1/Smad signaling pathway." (PMID 34671356, 2021). "ELISA detected the presence of shedding SDC-1 in the BALF, and the concentration of SDC-1 in mice with chronic asthma was higher than that in mice with acute asthma." (PMID 34671356, 2021). "However, SDC-1 expression remarkably increased in the tracheal epithelium and periductal of OVA-induced chronic asthma." (PMID 34671356, 2021). "The present results showed that SDC-1 and collagen deposition synchronously increased in humans and mice with chronic asthma, whereas that after SDC-1 shRNA intervention in mice or SDC-1 siRNA intervention in cells synchronously decreased to reduce SDC-1 level." (PMID 34671356, 2021).
Chronic colitis (1 paper, 2017). A chronic inflammatory disease of the large intestine (colon, cecum and rectum). "Our research was undertaken to elucidate the biological significance of Sdc1 in chronic colitis-associated tumorigenesis." (PMID 28350804, 2017). "A higher number of cells positive for nuclear-localized mucosal epithelial pSTAT3 was observed in the setting of DSS-induced chronic colitis in Sdc1-KO as compared to wt colon." (PMID 28350804, 2017). "Moreover, as shown by immunostainting, an elevated expression of the proinflammatory cytokine IL-6 [which is tightly implicated in the pathogenesis of human and experimental chronic colitis] was observed in DSS chronic colitis model in colons of Sdc1-KO as compared to wt mice." (PMID 28350804, 2017). "However, the biological significance of Sdc1 in chronic colitis-associated tumorigenesis has not been elucidated." (PMID 28350804, 2017). "Interestingly, several Sdc1-KO mouse-based inflammation-related models, including our experimental system of DSS-induced chronic colitis, have generally shown exacerbation in inflammatory processes upon Sdc1 deficiency." (PMID 28350804, 2017).
chronic myeloid leukemia (1 paper, 2020). "Furthermore, in mice, increased expression of syndecan-1 is associated with a therapy-resistant blastic crisis clone of chronic myeloid leukemia, and its loss is associated with marked improvement in survival." (PMID 32983743, 2020).
chronic obstructive pulmonary disease (1 paper, 2015). A chronic and progressive lung disorder characterized by the loss of elasticity of the bronchial tree and the air sacs, destruction of the air sacs wall, thickening of the bronchial wall, and mucous accumulation in the bronchial tree. "The stability and activity of inflammatory effectors, IL8 and neutrophil elastase (NE), can be prolonged by binding to airway heparan sulfate (HS)/syndecan-1, posing risk for developing chronic obstructive pulmonary disease(COPD)." (PMID 26256047, 2015).
clear cell carcinomas (1 paper, 2023). "Hasby E.A. analyzed the expression of syndecan-1 in HGSC, LGSC, and clear cell carcinomas and found that its expression was higher in HGSC and clear cell carcinoma compared to LGSC." (PMID 37370735, 2023).
cognitive decline (1 paper, 2025). "Importantly, the integrity of the blood–brain barrier is crucial in this context, and elevated levels of specific biomarkers like syndecan-1 can not only indicate the extent of endothelial damage but also forecast the trajectory of cognitive decline." (PMID 40989580, 2025).
coronary atherosclerosis (1 paper, 2022). Atherosclerosis of the coronary vasculature. "In a hyperlipemia-induced coronary atherosclerosis mice model, SDC1(−/−) mice showed hyperinflammation activity and greater atherosclerotic plaque disability." (PMID 35722091, 2022).
cutaneous squamous cell carcinoma (1 paper, 2024). "E-cadherin reduction and stromal syndecan-1 positivity seem to be associated with tumor aggressiveness in canine cutaneous squamous cell carcinoma." (PMID 39728992, 2024). "Syndecan-1 stromal positivity is significantly associated with higher histological grades in canine cutaneous squamous cell carcinoma, making it a potential diagnostic tool for tumor aggressiveness and prognostic marker." (PMID 39728992, 2024). "This study evaluated the expression of syndecan-1 and E-cadherin in 47 cases of canine cutaneous squamous cell carcinoma." (PMID 39728992, 2024). "Therefore, this study aims to evaluate the immunohistochemical expression of SDC1 and E-cadherin in canine cutaneous squamous cell carcinoma and to explore the relationship between these markers and the histological grade of malignancy." (PMID 39728992, 2024).
cystinosis (1 paper, 2025). Cystinosis is a metabolic disease characterized by an accumulation of cystine inside the lysosomes, causing damage in different organs and tissues, particularly in the kidneys and eyes. "The expression of SDC-1 and SDC-4 in the bladders of CYP-induced cystinosis mice was low and not significantly different, and the expression of SDC-2 and HPSE was significantly elevated in the CYP group." (PMID 40408331, 2025).
delirium (1 paper, 2021). A disorder characterized by confusion; inattentiveness; disorientation; illusions; hallucinations; agitation; and in some instances autonomic nervous system overactivity. "A specific relation between SDC1 and POD development was not demonstrated so far but it seems likely, since vascular and endothelial injury were shown to be associated with the pathogenesis of delirium in septic patients." (PMID 34063403, 2021).
diabetic angiopathy (1 paper, 2015). "Though studies showed HS mimetics/HPSE inhibitors (heparin, PI-88, SST001, etc.)fortify Sdc1 content of vascular endothelial cells and prevent the progression of diabetic angiopathy 39,40, there are few studies investigating whether they protect against HG-induced gastrointestinal damage." (PMID 25702768, 2015).
diabetic cardiomyopathy (1 paper, 2016). Diabetic cardiomyopathy is a disorder of the heart muscle in people with diabetes. "Membrane proteoglycans Gpc3 and Sdc1 have not yet been demonstrated to play a role in the development of diabetic cardiomyopathy, however, increased expression of the heparan sulfate proteoglycans Gpc1 and Sdc4 has been shown to lead to diastolic dysfunction in streptozotocin-induced diabetic rats." (PMID 27496100, 2016).
dilated cardiomyopathy (1 paper, 2016). Cardiomyopathy which is characterized by dilation and contractile dysfunction of the left and right ventricles. "Mice with deleted PECAM-1, Syndecan-1, and Syndecan-4 are healthy and fertile, although PECAM-1 knockouts suffer from dilated cardiomyopathy and systolic dysfunction." (PMID 27027326, 2016).
dyslipidaemia (1 paper, 2025). "Notably, SDC1 shedding in MetS may interfere with this process, as soluble ectodomains compete with cell‐bound SDC1 for lipoprotein binding, potentially contributing to dyslipidaemia." (PMID 41039734, 2025).
emphysema (1 paper, 2022). "Surprisingly, FGF10 increased the intensity of HS, CS and syndecan-1 even with a low dose of 10 or 100 μg/kg, while FGF10 attenuated emphysematous changes when the dose escalated to at least 1 mg/kg, indicating that glycocalyx repair is a process prior to repair of emphysema." (PMID 36183124, 2022).
End Stage Liver Disease (1 paper, 2022). Final stage of a liver disease when the liver failure is irreversible and LIVER TRANSPLANTATION is needed. "Increased baseline model for end-stage liver disease score, white cell count, calprotectin, CD163, tumor necrosis factor, renin, atrial natriuretic peptide, and syndecan-1 were associated with 3-month mortality." (PMID 35333783, 2022).
enthesitis (1 paper, 2026). Inflammation at the site of insertion of ligaments, tendons, and other fibrous structures into bone. "Specifically inhibiting SOX5 in enthesis fibroblasts via rAAV9.HAP-1 carrying a shRNA targeting Sox5 blocked the generation of SDC1+ sheath fibroblasts in response to mechanical strain and markedly reversed the development of CXCR4hi neutrophil-mediated enthesitis." (PMID 41637585, 2026).
femoral neck fracture (1 paper, 2024). Fractures of the short, constricted portion of the thigh bone between the femur head and the trochanters. "The immunohistochemical expressions of SDC1, SDC2, SDC4, EXT1, EXT2, NDST1 and NDST2 in synovial intima and subintima were then analysed and compared with the control group (patients with femoral neck fracture)." (PMID 38674142, 2024).
gestational diabetes (1 paper, 2016). Carbohydrate intolerance first diagnosed during pregnancy. "The aim of this pilot study was to determine the serum concentration of heparan sulfate, hyaluronan, chondroitin sulfate and syndecan-1 and if these serum concentrations can be used to identify women at 20 weeks' gestation who later develop gestational diabetes mellitus (GDM)." (PMID 27979833, 2016).
glomerulonephritis (1 paper, 2017). A renal disorder characterized by damage in the glomeruli. "Notably, increased leukocyte recruitment and increased expression of IL-6 and CCL2 in the absence of Sdc1 have been observed in other in vivo models of inflammation, including delayed-type hypersensitivity, glomerulonephritis, and autoimmune encephalomyelitis." (PMID 28350804, 2017).
gynecological cancers (1 paper, 2024). "Similarly, in gynecological cancers, estrogen receptor α signaling downregulates SDC1 expression." (PMID 39728992, 2024).
Heat Stroke (1 paper, 2025). A condition caused by the failure of body to dissipate heat in an excessively hot environment or during PHYSICAL EXERTION in a hot environment. "Heat stress induces glycocalyx shedding, as evidenced by fluorescence staining revealing diminished expression of glypican-1 (GPC-1) and SDC-1 in pulmonary vascular endothelia following heat stroke." (PMID 40703654, 2025). "Emerging studies reveal pathognomonic elevation of glycocalyx degradation products (specifically SDC-1, heparan sulfate, and hyaluronan) in both experimental heat stroke models and human patient plasma." (PMID 40703654, 2025). "Plasma SDC-1 and hyaluronic acid, which are components of the endothelial glycocalyx, gradually increased after the onset of heat stroke and peaked at 24 h." (PMID 40703654, 2025).
Hematochezia (1 paper, 2024). The passage of fresh (red) blood per anus, usually in or with stools. "When cyclophilin A (Cyp A) was added alone, group 3, hematochezia and diarrhea were both present in five mice out of eight in the wild-type mice, while seven of the syndecan-1 KO mice showed diarrhea and five suffered from hematochezia." (PMID 38276500, 2024). "In wild-type group 2, when DSS was used alone, six out of eight animals showed severe diarrhea and five suffered from hematochezia; in comparison, eight out of eight of the syndecan-1 KO mice showed severe diarrhea, and six mice suffered from hematochezia." (PMID 38276500, 2024).
hypopharynx cancer (1 paper, 2014). A primary or metastatic malignant neoplasm that affects the hypopharynx. "Furthermore, low serum syndecan-1 level can predict sensitivity to anticancer therapy in larynx and hypopharynx cancer, whereas high posttreatment level is an indicator of relapse." (PMID 25147801, 2014).
IgG4-related disease (1 paper, 2019). "Indeed, plasmablasts of IgG4-related disease patients express increased RNA levels of CD44 and SDC1 associated with cell migration and increased surface marker levels of activation markers such as HLA-DR, CD95." (PMID 31608054, 2019).
interstitial cystitis (1 paper, 2025). A rare chronic debilitating urogenital disease characterized by urinary frequency, urgency, and pelvic pain. "We found that heparanase 1 (HPSE) and syndecan-1 (SDC-1), syndecan-2 (SDC-2) and syndecan-4 (SDC-4) within the SDC family were up-regulated in the interstitial cystitis/bladder pain syndrome (IC/BPS) tissues." (PMID 40408331, 2025).
intrahepatic cholangiocarcinoma (1 paper, 2021). A carcinoma that arises from the intrahepatic bile duct epithelium in any site of the intrahepatic biliary tree. "In the TCGA cohort, high mRNA SDC1 levels were associated with poor prognosis in intrahepatic cholangiocarcinoma." (PMID 34206469, 2021). "Third, we did not compare different chemotherapy approaches for intrahepatic cholangiocarcinoma with syndecan-1 expression, although there may be an association." (PMID 34206469, 2021).
keratitis (1 paper, 2025). A corneal disease that is characterized by inflammation of the cornea. "The major source of HS is likely syndecan-1, because epithelial cells express large amounts of syndecan-1 on their cell surface and S. aureus activates syndecan-1 shedding via α-toxin, a major virulence factor of S. aureus keratitis." (PMID 41551642, 2025).
keratoacanthoma (1 paper, 2022). A dome-shaped, rapidly growing skin lesion composed of well differentiated squamous cells. "Thus, syndecan-1 staining was diminished in invasive SCC compared to in situ SCC and keratoacanthoma." (PMID 35572966, 2022).
lung diseases (1 paper, 2012). "Although SDC-1 and -4 have been implicated in fibrosis and have been suggested as targets for the treatment of lung diseases, we did not detect an increase of SDC-1, 3, or 4 in primary human fibroblasts in response to TGFβ or IGFBP-3." (PMID 22900087, 2012).
malignant pleural mesothelioma (1 paper, 2020). A malignant neoplasm that arises from mesothelial cells in the pleura and shows a diffuse growth pattern. "Here we show that the shed SDC-1 in contrast to the cell-bound SDC-1 indicates poor prognosis in both malignant pleural mesothelioma and metastatic adenocarcinoma patients." (PMID 32731396, 2020). "Taken together, candidate biomarkers (Galectin-1, Mesothelin, Osteopontin, shed SDC-1, VEGF, MMP-7, HGF, TIMP-1 and NRG1-β1) identified in the current study could be diagnostic biomarkers for distinguishing malignant pleural mesothelioma and metastatic adenocarcinoma from benign patients." (PMID 32731396, 2020). "Our results clearly suggest that SDC-1 and VEGF can serve as prognostic biomarkers for malignant pleural mesothelioma." (PMID 32731396, 2020). "Shed SDC-1 and VEGF are prognostic biomarkers for malignant pleural mesothelioma." (PMID 32731396, 2020).
mucoepidermoid carcinoma (1 paper, 2021). A carcinoma morphologically characterized the presence of cuboidal mucous cells, goblet-like mucous cells, squamoid cells, cystic changes, and a fibrotic stromal formation. "Syndecan-1 was expressed in both epithelial and stromal components of all mucoepidermoid carcinomas (100%)." (PMID 31540870, 2021). "The Spearman test showed a statistically significant negative correlation between stromal percentage of syndecan-1 and age in the mucoepidermoid carcinoma group (p = 0.01, r = −0.43)." (PMID 31540870, 2021).
mycoplasmosis (1 paper, 2024). "Syndecan-1 and ET-1 concentrations of cats with hemotropic mycoplasmosis were significantly higher than the healthy ones (p < 0.001)." (PMID 38839816, 2024).
myeloid leukemia (1 paper, 2020). A clonal proliferation of myeloid cells and their precursors in the bone marrow, peripheral blood, and spleen. "The current work adds further insight not only in identifying Itgβ7 as an element in myeloid leukemia but also in defining a role for Sdc1 in coordinating integrin activity in hematologic malignancies." (PMID 33243988, 2020). "Most importantly, this approach identified multiple surface molecules whose role in myeloid leukemia remains unknown; these included integrin β7, siglec-F (CD170), CD72, LPAM-1 (integrin α4β7) and syndecan-1 (Sdc1, CD138)." (PMID 33243988, 2020).
Myocardial fibrosis (1 paper, 2019). "Syndecan-1 deficiency, in vivo and in fibroblasts, blunted the Ang II-induced rise in expression of CTGF, collagen type I, and Smad2 phosphorylation as well as myocardial fibrosis." (PMID 31547598, 2019).
myoepithelioma (1 paper, 2021). "We observed high syndecan-1 expression in tumor cells in two cases of basal cell adenoma and myoepithelioma." (PMID 31540870, 2021).
neck cancer (1 paper, 2024). "Recent evidence supports the relevance of the coupling of the IGF1R extracellular domain to a matrix adhesion receptor complex consisting of syndecan-1 (Sdc1) and αvβ3 or αvβ5 integrin for promoting cell growth and migration of neck cancer cells." (PMID 38892104, 2024).